MMP12 (matrix metallopeptidase 12)
Diseases named in the same sentence as MMP12 in open-access papers (continued):
Sharing a sentence is not in itself a finding about the gene and the disease.
pulmonary fibrosis (continued). "Immunohistochemistry and Western blotting were performed to observe changes in proteins related to pulmonary fibrosis (α-smooth muscle actin (α-SMA) and matrix metalloproteinase 12 (MMP12)) and autophagy (P62 and mechanistic target of rapamycin (mTOR))." (PMID 38361765, 2024). "In conclusion, this study shows that praziquantel can ameliorate BLM-induced pulmonary fibrosis in mice by affecting the balance of M2/M1 macrophages and suppressing the expression of TGF-β and MMP-12." (PMID 38355586, 2024). "MMP12 is increased in serum and lung tissues of SSc patients with ILD and positively correlates with lung fibrosis severity." (PMID 34512395, 2021). "However, MMP-12 involvement in pulmonary fibrosis is unknown." (PMID 16504062, 2006). "In our experimental model of pulmonary fibrosis, TGF-β-1 protein was induced similarly in both MMP-12 -/- and WT mice." (PMID 16504062, 2006). "Our study demonstrated that PZQ could ameliorate BLM-induced pulmonary fibrosis in mice by affecting the balance of M2/M1 macrophages and suppressing the expression of TGF-β and MMP-12." (PMID 38355586, 2024). "The marker gene selected may be related to the disease, for example the gene Mmp12 was considered a subset macrophage marker (AM3) and AM3 was predominantly present in the BLM-induced fibrosis group, while Mmp12 is reported to participate in lung fibrosis." (PMID 36211428, 2022). "While MMP12 functions in SSc-ILD have not been defined, MMP12 downregulated expression of collagenase MMP13 in a Schistosoma mansoni Th2-driven model of lung fibrosis, providing a crucial example of MMP-dependent regulation of other metalloproteinases." (PMID 34512395, 2021).
chronic obstructive pulmonary disease (36 papers, 2005 to 2025). A chronic and progressive lung disorder characterized by the loss of elasticity of the bronchial tree and the air sacs, destruction of the air sacs wall, thickening of the bronchial wall, and mucous accumulation in the bronchial tree. "MMP12 is associated with elastin degradation and macrophage migration in various diseases, such as chronic obstructive pulmonary disease, skin diseases and cancers." (PMID 33935718, 2021). "Upon searching the Open Targets platform, we identified 10 known small molecule drugs in clinical trials (including LY2584702) that are linked to two proteins (RPS6KB1 and MMP12), targeting various cancers, chronic hepatitis C infection and chronic obstructive pulmonary disease." (PMID 40092369, 2025). "As matrix metalloproteinases (MMPs), especially MMP-9 and MMP-12 are involved in the pathological processes associated with chronic obstructive pulmonary disease (COPD), we developed a novel radiofluorinated probe, 18F-IPFP, for MMPs-targeted positron emission tomography (PET)." (PMID 29358724, 2018). "MMP12 is expressed in alveolar macrophages of smokers with chronic obstructive pulmonary disease (COPD), but is rarely detected in healthy macrophages." (PMID 40496925, 2025). "Alveolar macrophages (AMs) and AM-produced matrix metalloprotease (MMP)-12 are known to play critical roles in the pathogenesis of chronic obstructive pulmonary disease (COPD)." (PMID 37592330, 2023). "Previous studies have found that MMP12-generated elastin fragments act as an autoantigen to drive the autoimmune process in chronic obstructive pulmonary disease (COPD) mouse models." (PMID 37176151, 2023). "Studies have shown that MMP-12 is involved in chronic obstructive pulmonary disease (COPD), emphysema, asthma, and arthritis." (PMID 37513440, 2023). "MMP12 plays a pivotal role in inflammatory diseases, such as colitis and chronic obstructive pulmonary disease." (PMID 34552928, 2021). "Related to its implication in the effects of the exposure to cigarette smoke, MMP-12 is a key enzyme in diseases such as chronic obstructive pulmonary disease (COPD) and has been proposed as an early biomarker due to its elevated levels in tissue sampling." (PMID 31426440, 2019). "Excess macrophage elastase MMP-12 is a major driver of chronic obstructive pulmonary disease." (PMID 35031603, 2022). "Increased MMP-12 production is often observed in chronic obstructive pulmonary disease (COPD)." (PMID 34703996, 2021). "MMP-1, MMP-8, MMP-9 and MMP-12 have been shown to be upregulated in the disease region of chronic obstructed pulmonary disease (COPD), which is a chronic inflammatory airway disorder commonly caused by cigarette smoking and occupational inhalation (e.g., dust or chemicals)." (PMID 32586313, 2020). "MMP12 is recognized as degrading soluble and insoluble elastin; inducing pro-osteogenic calcification in aortic valve disease; and playing a role in aneurysm formation, lung dysfunction, and chronic obstructive pulmonary disease." (PMID 32098116, 2020). "We evaluated the MMP-12 since this metalloproteinase is able to degrade extracellular matrix components and is involved in lung tissue remodeling observed in inflammatory pulmonary diseases such as chronic obstructive pulmonary diseases (COPD)." (PMID 30984425, 2019). "Hyperactivity of MMP12 in the lung can be induced by cigarette smoke in humans and reduces the elasticity of alveoli, which contributes to an incomplete emptying of the lung in chronic obstructive pulmonary disease patients." (PMID 29572503, 2018). "Beyond its traditional association with pulmonary diseases like chronic obstructive pulmonary disease (COPD), MMP12 has increasingly been recognized for its role in cancer biology." (PMID 41465234, 2025). "MMP-12 is involved in cancer and several chronic pulmonary inflammatory diseases such as chronic obstructive pulmonary disease (COPD), asthma and IPF." (PMID 35805895, 2022).
chronic obstructive pulmonary disease (continued). "In cigarette smoke-induced chronic obstructive pulmonary disease (COPD), Mmp12−/− mice show reduced emphysema and inflammation reactions in the lung." (PMID 33800947, 2021). "In diseases such as chronic obstructive pulmonary disease (COPD), it has been shown that AAT is capable of inhibiting the action of MMP-12." (PMID 25723058, 2014). "ACP was also found to overexpress MMP9 (FC = 41.0, p = 9.8 × 10−14) and, more strikingly, MMP12 (FC = 819.7, p = 3.0 × 10−49), which are both inhibited by AZD1236, a drug originally tested as a treatment for chronic obstructive pulmonary disease, but more recently investigated as an antitumor agent." (PMID 25990246, 2015). "A previous study have reported that the expression and secretion of MMP-12 can be regulated by IL-1β and TNF-α in human airway smooth muscle cells, and thereby participated in diseases of the airway, such as chronic asthma or chronic obstructive pulmonary diseases (COPD)." (PMID 33935718, 2021). "The purpose of this study was to compare matrix metalloproteinase-12 (MMP-12), neutrophil elastase (NE), and tissue inhibitor of metalloproteinase-4 (TIMP-4) in peripheral blood of patients with chronic obstructive pulmonary disease (COPD) and controls." (PMID 31143784, 2019).
lung carcinoma (30 papers, 2007 to 2025). "The development and occurrence of malignant tumors, including lung cancer, epithelial ovarian cancer, and breast cancer, are closely associated with MMP-12 expression." (PMID 38511770, 2024). "PLAU and MMP12 have been reported to be associated with aberrant regulation of gene function and poor prognosis for lung carcinoma." (PMID 33072067, 2020). "Up-regulated MMP12 has been found associated with the pathological stage and tumor metastasis in lung cancer." (PMID 32411535, 2020). "Gene expression analysis confirmed successful target engagement, showing universal MMP12 downregulation and coherent modulation of its predicted downstream signaling network in treated lung cancer cells." (PMID 41465234, 2025). "This study enhances our understanding of MMP12, an understudied therapeutic target in lung cancer, by combining computational biology with comprehensive cellular and molecular validation." (PMID 41465234, 2025). "This study established an integrative, informatics- and network-guided framework to evaluate MMP12 as a therapeutic target in lung cancer." (PMID 41465234, 2025). "Collectively, these findings highlight C1, C7, C9, C10, and C15 as promising MMP12 inhibitors, supporting their further development in preclinical lung cancer and nominating the eight-gene panel as a pharmacodynamic signature for MMP12-targeted therapies." (PMID 41465234, 2025). "An initial baseline assessment of MMP12 expression across three untreated lung cancer cell lines (H1299, A549, and H661) using the 2−ΔCt method identified H661 as the highest expressor, followed by H1299, and A549 as the lowest." (PMID 41465234, 2025). "Quantitative real-time PCR (qPCR) was used to assess the impact of MMP12 inhibition in H1299 lung cancer cells." (PMID 41465234, 2025). "To examine the systems biology of MMP12 in lung cancer pathogenesis, we first established a framework of disease-relevant genes using the MetaCoreTM database." (PMID 41465234, 2025). "Prior to treatment, baseline MMP12 levels were assessed in untreated lung cancer cell lines H1299, A549, and H661, with H1299 showing the highest expression." (PMID 41465234, 2025). "Collectively, these results confirm the efficacy of the intervention in engaging MMP12, modulating downstream effectors, and reshaping the molecular landscape of lung cancer cells toward a less invasive and less inflammatory state." (PMID 41465234, 2025). "These overlapping genes represent high-priority candidates, suggesting a functional convergence between MMP12 activity and established pathways in lung cancer development, apoptosis, and migration." (PMID 41465234, 2025). "MMP12 is upregulated in a variety of cancers and its expression is correlated with poor prognosis, such as gastric, liver, intestinal and lung cancers." (PMID 35313071, 2022). "The level of MMP-12 appears to be highly expressed in a wide range of cancers, including colorectal, gastric, skin nasopharyngeal, and lung cancer." (PMID 33892690, 2021). "MMP12 protein is overexpressed in lung cancer and correlates with local recurrence and metastasis, as well as with early cancer-related deaths in non-small cell lung cancer patients." (PMID 34912233, 2021). "Aberrant expression of MMP12 was reported in several types of cancers, including hepatocellular carcinoma, lung cancer, colon cancer and nasopharyngeal carcinoma." (PMID 33935718, 2021). "Another recent study showed that MMP-12 mRNA levels were increased in tumor cells of lung cancer patients." (PMID 34912233, 2021). "This correlative result between MMP-12 mRNA levels and diminished lung cancer survival was also found in other studies." (PMID 34912233, 2021). "Marked changes in gene expression were measured for Ccl2, Ccl7, Ccl17, Ccl22, Ccl3, Ccl4, Il-1α, Il-1ß, and Il-1rn (inflammation), Lpo and Noxo1 (oxidative stress), and Mmp12 (inflammation/lung cancer)." (PMID 29463257, 2018).
lung carcinoma (continued). "This is likely to be functionally relevant, since increased levels of MMP‐12 in myeloid cells promoted lung tumorigenesis in mice and correlated with high malignancy in human lung cancer." (PMID 27932444, 2017). "In patients with lung cancer, macrophage elastase (MMP-12) and gelatinase (MMP-9) have been shown to promote lung tumour growth." (PMID 26316944, 2014). "MMP-3 has a protective role in squamous cell carcinoma and macrophage MMP-12 is an anti-target in lung carcinoma." (PMID 17375198, 2007). "The central hypothesis of this study is that targeted inhibition of MMP12 disrupts key oncogenic networks, as measured by specific genomic biomarkers, leading to suppressed lung cancer cell growth and metastatic potential." (PMID 41465234, 2025). "This underscores the role of matrix metalloproteinases, such as MMP12, in lung cancer development." (PMID 41465234, 2025). "Building on a previous study on recently validated MMP12 inhibitors, this study aims to characterize the anticancer potential of selected MMP12 inhibitor candidates, identify associated genomic biomarkers, and define the mechanistic consequences of MMP12 suppression in lung cancer." (PMID 41465234, 2025). "Thus, substantial evidence points to MMP-12 being significantly up-regulated in human lung cancer samples." (PMID 34912233, 2021). "Studies, however, have found elevated levels of MMP-12 in malignant lung tumors." (PMID 34912233, 2021). "MMP7 and MMP12 levels are elevated in lung cancer, which may facilitate breakdown of the extracellular matrix and tumor spread." (PMID 25114662, 2014). "Strikingly, these cultures also express elevated Mmp10 mRNA, but no increase in Mmp2, Mmp7, Mmp9, Mmp11, Mmp12 or Mmp14, other Mmp species commonly linked to lung cancer." (PMID 22545096, 2012). "Therefore, MMP12 knockdown inhibited proliferation and invasion of nasopharyngeal and lung cancers." (PMID 35741697, 2022). "However, due to the upregulation of Mmp12 a relation to potential long-term effects like fibrosis and lung cancer could be assumed." (PMID 29463257, 2018). "Given the strong involvement of MMP12 in tumor invasion, inflammation, and ECM remodeling, its activity is particularly relevant in lung cancer biology." (PMID 41465234, 2025). "Using the Lung Cancer Explorer platform, we observed that MCM4 expression was positively correlated with MMP9 and MMP12 across both TCGA and GSE32863 datasets, supporting a potential role of MCM4 in promoting ECM degradation and invasion." (PMID 40564876, 2025). "As a result, targeting MMP12 is particularly relevant in NSCLC, making it the most suitable model for investigating its role in lung cancer progression and metastasis." (PMID 41465234, 2025). "qRT-PCR and immunohistochemistry indicated that several key molecules such as Osteopontin/Spp1, Hmox1, Mmp12, and ERBB2 were markedly altered and/or localized in the preneoplastic lesions, suggesting their participation in the induction of lung cancer." (PMID 37513116, 2023). "The results showed that the expression of MMP9 and MMP12 in lung cancer tissues was higher than that in normal tissues adjacent to cancer, and the expression of CD36 and FABP4 in lung cancer tissues was lower than that in normal tissues adjacent to cancer." (PMID 37978381, 2023). "In particular, MMP2 and MMP12 have been shown to degrade components of the ECM and correlate with lung cancer metastasis." (PMID 36241874, 2022). "Collectively, these data suggest that CM from CAFs exposed to apoptotic cancer cells inhibits the migration and invasion of lung cancer cells via inhibition of TGF-β1 signaling-related pathways as well as MMP-2 and MMP-12 expression." (PMID 36241874, 2022). "Collectively, these data indicate that the interaction of CAFs with apoptotic lung cancer cells inhibits CAF migration and invasion via inhibition of TGF-β1 signaling pathways as well as MMP-2 and MMP-12 expression." (PMID 36241874, 2022).
lung carcinoma (continued). "In the lung cancer model, in utero exposures to SHS significantly increased the number of intrapulmonary metastases at 58weeks of age and up-regulated Mmp12 (9.3-fold compared to air-urethane controls)." (PMID 34912233, 2021). "Interestingly, our analysis also found that lung cancer cell lines with higher OXPHOS (MMP3 and MMP12) and CAC (MMP5) were more sensitive to elesclomol, consistent with previous study, supporting the reliance of our analysis results." (PMID 39393173, 2024). "MMP12 expression induced the EMT reprogramming and contributed to metastasis in lung cancer." (PMID 39528470, 2024). "Using IPA’s Biomarker Filter (Homo sapiens; cancer; lung cancer cell lines), three genes in our panel mapped to established biomarkers (not specifically for MMP12 inhibition): ADAM9 (efficacy/prognosis), CD44 (diagnosis/progression/prognosis), and MMP12 (efficacy)." (PMID 41465234, 2025). "Furthermore, compared to air urethane controls, in the urethane-induced lung cancer model, in utero exposures to SHS significantly increased the volume of the tumors, as well as the number of intrapulmonary metastases, and up-regulated Mmp12 (9.3-fold) in 58-week-old female mouse offspring." (PMID 34912233, 2021).